ARPP21 (cAMP regulated phosphoprotein 21)
Description:
Isoform 2 may act as a competitive inhibitor of calmodulin-dependent enzymes such as calcineurin in neurons.
Synonyms: ARPP-21; TARPP; R3HDM3; RCS
Tractability: PROTAC: ubiquitination databases record sites on it.
Gene: Protein-coding gene on chromosome 3 (35,638,945 to 35,794,496, forward strand). Ensembl gene ENSG00000172995.
Subcellular location: Cytoplasm
Subcellular location (Human Protein Atlas): Nucleoli; Cytosol
Gene Ontology:
Molecular function: nucleic acid binding
Cellular component: cytoplasm
Genetic constraint (gnomAD): Loss-of-function variants: 45 observed, 81.14 expected, observed/expected ratio (o/e) 0.55, 90% interval 0.44 to 0.71. The upper end of that interval is the gene's LOEUF score, 0.71, which puts it in group 2 of 6, group 1 being the genes least tolerant of losing a copy. Missense variants: 871 observed, 882.85 expected, observed/expected ratio (o/e) 0.99, 90% interval 0.93 to 1.04. Synonymous variants: 317 observed, 331.77 expected, observed/expected ratio (o/e) 0.96, 90% interval 0.87 to 1.05.
Gene-disease validity (ClinGen):
ClinGen rates the evidence that ARPP21 causes each of these diseases.
amyotrophic lateral sclerosis (autosomal dominant): Limited. Amyotrophic lateral sclerosis (ALS) is a neurodegenerative disease characterized by progressive muscular paralysis reflecting degeneration of motor neurons in the primary motor cortex, corticospinal tracts, brainstem and spinal cord.
Homologues: Orthologues: chimpanzee ARPP21 (99% identical), macaque ARPP21 (99% identical), rabbit ARPP21 (95% identical), guinea pig ARPP21 (92% identical), pig ARPP21 (88% identical), rat Arpp21 (87% identical), mouse Arpp21 (83% identical), Drosophila melanogaster enc (28% identical), Caenorhabditis elegans ZK121.2 (17% identical). Paralogues in human: R3HDM1 (52% identical), R3HDM2 (41% identical).
Diseases named in the same sentence as ARPP21 in open-access papers:
ARPP21 is named in the same sentence as 27 diseases in open-access papers, as found by Europe PMC text mining. Sharing a sentence is not in itself a finding about the gene and the disease. The quoted sentences say what the papers report.
breast carcinoma (2 papers, 2015 to 2021). "Mechanistically, MIR128-1 downregulates ARPP21 (CAMP-regulated phosphoprotein 21) gene, a crucial gene that inhibits apoptosis and confers increased chemo-radiotherapy resistance in breast cancer cells." (PMID 33920789, 2021). "ARPP21 is frequently downregulated, as is miR-128-2, in human breast cancer." (PMID 25351872, 2015).
epilepsy (2 papers, 2022 to 2024). A brain disorder characterized by episodes of abnormally increased neuronal discharge resulting in transient episodes of sensory or motor neurological dysfunction, or psychic dysfunction. "Arpp21 and the autism gene Grin2b, that control dendritogenesis and branching were also Gatad2b dosage-sensitive genes differentially expressed in more than one cell cluster, with Grin2b being clinically associated with epilepsy and autism." (PMID 38238293, 2024).
Intellectual disability (2 papers, 2017 to 2018). "To test our model of functional antagonism between miR-128 and ARPP21 in development we chose the intellectual disability gene Phf6 as a highly ranked ARPP21 target in the iCLIP experiment." (PMID 29581509, 2018).
lung carcinoma (2 papers, 2015 to 2022). "Loss of miR-128 has been reported in human lung cancer—due to a deletion on chromosome 3p that includes the miR-128-2 and ARPP21 locus—and in breast cancer." (PMID 36793341, 2022).
Obesity (2 papers, 2022). Accumulation of substantial excess body fat. "The colocalization analysis implicates genes involved in body mass index (BMI)/obesity and neuroticism (ARPP21, RP11-62H7.2, MFHAS1, RHEBL1)." (PMID 36297114, 2022).
acute myeloid leukemia (1 paper, 2022). Acute myeloid leukemia (AML) is a group of neoplasms arising from precursor cells committed to the myeloid cell-line differentiation. "According to a study by Mi and colleagues, intronic miR-128-2, which is located in an intron of cAMP-regulated phosphoprotein 21 (ARPP21), was significantly upregulated in all subjects but not in acute myeloid leukemia (AML)." (PMID 36793341, 2022).
Anxiety (1 paper, 2015). Intense feelings of nervousness, tension, or panic often arise in response to interpersonal stresses. "Recent studies have begun to relate MIR-128 and ARPP21 with neuropsychiatric disorders such as fear response, anxiety, intellectual disability and in movement disorders." (PMID 26696825, 2015).
Brain atrophy (1 paper, 2023). Partial or complete wasting (loss) of brain tissue that was once present. "The genetic variant near ARPP21 associated with lower cognitive scores in the A4 and accelerated cognitive decline and brain atrophy in the ADNI may help to identify those at the highest risk of accelerated progression of AD." (PMID 37085326, 2023).
glioma (1 paper, 2022). A benign or malignant brain and spinal cord tumor that arises from glial cells (astrocytes, oligodendrocytes, ependymal cells). "Other SHH-1A associated genes were the neuroendocrine-specific tumor genes SST and SCG2; ARPP21, encoding an RNA-binding protein found in glioma, and SOX6, a tumor marker expressed by not fully differentiated neuronal and glial cells." (PMID 35501487, 2022).
Huntington disease (1 paper, 2021). Huntington disease (HD) is a rare neurodegenerative disorder of the central nervous system characterized by unwanted choreatic movements, behavioral and psychiatric disturbances and dementia. "We finally screened five genes, including Arpp21, Rgs4, Rasd2, Gabrd, and Tmod1, two (Arpp21 and Rasd2) of which have been reported to be related with Huntington’s disease." (PMID 34433483, 2021).
mastitis (1 paper, 2023). Inflammation of breast tissue during lactation or postpartum due to an obstructed duct or infection. "Polycystic kidney and liver disease 1 (PKHD1), inducible T-cell co-stimulatory factor (ICOS), and cAMP-regulated phosphoprotein 21 (ARPP21) enhance mastitis resistance." (PMID 38028584, 2023).
Omenn syndrome (1 paper, 2024). An inflammatory condition characterized by erythroderma, desquamation, alopecia, chronic diarrhea, failure to thrive, lymphadenopathy, and hepatosplenomegaly, associated with severe combined immunodeficiency (SCID). "In fact, the shift towards proximal TRAV fragment usage is seen in Omenn syndrome patients and similarly found in Arpp21–/– and Rag13’del/3’del mice." (PMID 38467629, 2024).
tumor (3 papers, 2015 to 2022). "Additionally, ARPP21 encodes a 21-kDa cAMP-regulated phosphoprotein termed regulator of calmodulin signaling, which is enriched in the brain and may serve as a candidate tumor suppressor gene." (PMID 25351872, 2015).
infection (2 papers, 2021 to 2025). The state of being infected such as from the introduction of a foreign agent such as serum, vaccine, antigenic substance or organism. "MA10 infection induced seven additional down-regulated (Hsp90aa1, Tcf7l2, Gnas, Sparcl1, Ywhag, Cpe, Sparc) and four upregulated DEGs (Ppp1r1b, Penk, Arpp21, Pcp4), whereas Aβ pathology resulted in five down-regulated (Cplx1, Syp, Meg3, Snhg11, Penk) and one upregulated DEG (Psen1)." (PMID 41497643, 2025). "Furthermore, the ARPP21 gene was downregulated after 2 h of infection with S. Typhi in a transcriptome study of human intestinal tissue after early infection." (PMID 34074014, 2021).
ARPP21 also shares sentences with these, for which no sentence is quoted: Alzheimer disease (3 papers); cancer (2); acute lymphoblastic leukemia (1); alopecia (1); amyotrophic lateral sclerosis (1); autism (1); autism spectrum disorder (1); Autoimmunity (1); cognitive decline (1); malaria (1); Parkinson disease (1); schizophrenia (1); Stroke (1).